FAP (fibroblast activation protein alpha)
Diseases named in the same sentence as FAP in open-access papers (continued):
Sharing a sentence is not in itself a finding about the gene and the disease.
tumor (continued). "Digital pathology combined with AI-assisted image analysis was employed to quantify and visualize the spatial distribution of OSCC cells (RANKL-positive), CAFs (α-SMA and FAP-positive), and osteoclasts (cathepsin K-positive) within defined regions of interest at the tumor–bone invasive front." (PMID 41153834, 2025). "Another possible reason is the tumor microenvironment: Lesions in the liver and lung may have similar FAP expression or lytic activity as the organs themselves, reducing tracer contrast." (PMID 41301015, 2025). "Thus, we utilized the FAP+ cell population to represent apCAFs to investigate relationships between apCAFs and tumor progression and prognosis." (PMID 39891284, 2025). "Interestingly, while the depletion of FAP+ CAFs results in increased animal survival, the depletion of CAFs expressing alpha smooth muscle actin (αSMA) leads to increased tumor growth and decreased animal survival." (PMID 40723238, 2025). "Therefore, FAP-targeted imaging can accurately outline the tumor boundary of tumors with remarkably mesenchymal hyperplasia." (PMID 40438601, 2025). "For instance, the high expression of the classic CAF marker FAP in ductal carcinoma in situ (DCIS) indicates strong tumor invasiveness and poor prognosis, whereas in invasive ductal carcinoma (IDC), it is significantly correlated with longer overall survival (OS) and disease-free survival (DFS)." (PMID 40890855, 2025). "(2025) demonstrated that tumor cells at the leading-edge area of iCCA exhibit enhanced proliferation and are closely associated with stromal components, including endothelial cells and POSTN+ FAP+ fibroblasts." (PMID 41394868, 2025). "Also, we identify stromal antigens, previously targeted to manipulate the TME, as tumor cell intrinsic in STS like FAP, FOLR2, or CD248." (PMID 40814001, 2025). "Notably, while the MAGEA4 protein was exclusively detected in the tumor cells, FAP was observed in both tumor and surrounding stroma cells." (PMID 41345672, 2025). "Additionally, canonical CAF markers ACTA2 and FAP exhibited elevated expression levels in tumor samples." (PMID 40771797, 2025). "In addition, upregulation in the fibroblast activation protein (FAP), which is known to be expressed in tumor mesenchymal and epithelial cells, enhances migration and invasion." (PMID 40075679, 2025). "FAP modulates the extracellular matrix through both enzymatic degradation and non-enzymatic scaffolding effects, contributing to increased tissue stiffness and tumor invasiveness." (PMID 41303595, 2025). "Notably, genes associated with metastasis, such as MMP2 and FAP, were upregulated in TRPM8 KO samples, indicating a potential role for TRPM8 in inhibiting tumor invasion." (PMID 40214455, 2025). "Notably, immunization of mice with DCs transfected with fibroblast activation protein (FAP) mRNA led to significant antitumor responses, highlighting FAP as a potential tumor rejection antigen in a variety of cancers." (PMID 40453074, 2025). "Two FAP-targeting bimodal ligands were synthesized and evaluated in vitro and in vivo, showing high specificity and selectivity, along with rapid and selective tumor accumulation." (PMID 41348275, 2025). "The use of FAP-specific chimeric antigen receptor T-cell therapy has been reported to be able to eliminate most FAP positive CAFs and decrease tumour stromal generation; however, significant side effects were observed, especially with respect to bone marrow toxicity." (PMID 41373503, 2025). "While not yet used in routine clinical practice, FAP expression has been associated across several solid tumors with greater tumor aggressiveness and worse survival outcomes." (PMID 41303595, 2025). "EGFR and IDH1 were highly expressed in tumor cells, FAP and COL1A1 were confined to fibroblasts, CD68 and ITGAM marked macrophages, PECAM1 and CDH5 identified endothelial cells, OLIG2 and MOG were specific to oligodendrocytes, while CD4 and CD3D defined T-cell subsets." (PMID 41208987, 2025).
tumor (continued). "High FAP expression has been correlated with enhanced tumour growth and metastatic potential." (PMID 39780187, 2025). "Depletion of FAP+ CAFs enhances T cell infiltration in the tumor." (PMID 40438601, 2025). "The surface marker of CAFs, FAP, is also involved in tumor immunosuppression." (PMID 40485724, 2025). "Indeed, an IL-2v immunocytokine targeting PD-1 in cis (named PD1-IL-2v) and directed to the FAP tumor stroma antigen has been developed." (PMID 39852848, 2025). "At the same time, the use of FAP inhibitor Talabostat (PT100) might also be one of the options to improve the efficacy of tumor treatment." (PMID 40626005, 2025). "Moreover, considering the use of a tumour model with natural FAP-expression and the very low activity injected, the significance of the results is further heightened." (PMID 40762892, 2025). "Additionally, the abundance of FAP + CAFs was proportionally correlated with that of lymphoid and myeloid cells in both tumor regions." (PMID 39751643, 2025). "High infiltration level of FAP+ fibroblasts infiltration also contributes to the formation of a desmoplastic microenvironment through laminin pathways and other intercellular signals creating conditions unfavorable for anti-tumor immunity." (PMID 40438108, 2025). "Consistent with previous studies 88, we observed significant upregulation of FAPα and matrix metalloproteinase 9 (MMP9) across the majority of cancer types analyzed, highlighting their relevance in tumour biology, as they have been associated to tumour progression and/or metastasis." (PMID 40083695, 2025). "Notably, FAP exhibited a positive correlation (r ≈ 0.4, p < 0.01) with genes involved in angiogenesis and tumor microenvironment remodeling, including VEGFA, HIF1α, and EGFR." (PMID 40430845, 2025). "Interestingly, when correlating the serum sFAP levels and tumor tissue FAP expression in DLBCL and FL, we observed two interesting patterns." (PMID 41373408, 2025). "This FAP-driven phenotype highlights its dual role in both tumor progression and immune evasion." (PMID 41233863, 2025). "In addition to its expression on stromal cells, FAP has also been detected on the surface of tumour cells in selected malignancies, including pancreatic ductal adenocarcinoma, sarcoma, colorectal cancer, and gastric cancer." (PMID 41228206, 2025). "Subpopulations such as α-SMA+/FAP− or α-SMA−/FAP+ fibroblasts may be overlooked, despite their potential to exert unique effects on tumor progression, immune modulation, extracellular matrix remodeling, or osteoclastogenesis." (PMID 41153834, 2025). "FAP-RLT is emerging as a promising pan-tumor targeted therapy." (PMID 41425958, 2025). "The failure of these trials may be attributed to the heterogeneous nature of cancer-associated fibroblasts (CAFs) and the function of fibroblast activation protein (FAP), which can promote tumorigenesis in certain tumours while inhibiting it in others." (PMID 40741380, 2025). "The substitution of the DOTA chelator with the AAZTA ligand on FAPI-46 moiety allowed a fast radiolabelling at room temperature of the PET tracer without influencing the biodistribution properties, such as clearance and FAP-mediated tumor uptake, but rather expanding the tracer applicability." (PMID 40762892, 2025). "Moreover, tumor-associated (MKI67) and CAF-related (FAP, Fibronectin, COL1A1) genes were downregulated in the FAP/IL-15 CAR-T group compared to other groups." (PMID 41455698, 2025). "FAP is expressed in many cancers and contributes to tumour progression and metastasis." (PMID 40741380, 2025). "FAP has been shown to promote tumour invasion through several mechanisms." (PMID 40741380, 2025). "Notably, [89Zr]Zr-B12 IgG demonstrated significantly enhanced tumor uptake in FAP-positive cells in mice bearing CWR-R1FAP relative to the control group injected with [89Zr]Zr-IC IgG." (PMID 38543239, 2024).
tumor (continued). "Furthermore, FAP expression was observed to be higher in tumor samples compared to AL, which was consistent with the IHC results, and further supported by IF analysis." (PMID 39239526, 2024). "Besides, early response evaluation during and after therapy is possible with 68Ga-FAPI PET/CT scans, as FAP is part of the tumor microenvironment and molecular changes in the tumor stroma can subsequently be depicted." (PMID 38505595, 2024). "FAP-targeted NIR-PIT had minimal effect compared to the control group in CAF-poor tumor models." (PMID 38555315, 2024). "Most studies have confirmed that FAP has a tumor-promoting effect and could be a promising target molecule for the diagnosis and treatment of tumors." (PMID 38740736, 2024). "The benign non-tumor pulmonary lesions’ lower mean SUVmax could be attributed to the relatively reduced expression of FAP in pulmonary interstitial fibroblasts compared to tumor-associated fibroblasts." (PMID 38779097, 2024). "FAPα is highly expressed in tumor tissues but poorly expressed in monolayer-culture conditions." (PMID 39596363, 2024). "We further investigated the effect of FAP+ fibroblasts on tumor cells." (PMID 39095854, 2024). "FAP-radioligands, which act through different mechanisms based on FAP expression on CAFs and also on certain tumor cells, deliver ionizing radiation directly to CAF or tumor cells and may affect nearby cells through crossfire effects." (PMID 38540204, 2024). "Notably, we observed that the larger and more necrotic U-87 MG xenografts had higher FAP-expression than the small and slower growing U-87 MG xenografts in our sample set, resulting in both intra- and inter-tumor heterogeneity." (PMID 39718718, 2024). "The dual-targeting PET tracer 68Ga-NOTA-FAPI-RGD, designed to target both FAP and integrin αvβ3, demonstrated significantly enhanced tumor uptake, retention, and TBR compared to its monomeric counterparts 68Ga-FAPI-02 and 68Ga-RGDfK in preclinical pancreatic tumor models." (PMID 39598465, 2024). "With ECM remodeling already being known as an important process in tumor progression, more knowledge of the precise role of the protease activity of FAP in the TME could be key to better understanding the disease and treatment strategies." (PMID 38540158, 2024). "CCA FAP expression was compared to clinical and tumor pathology features." (PMID 39664608, 2024). "Such innovations hold significant potential for advancing clinical FAP-targeted tumor therapy." (PMID 38543239, 2024). "Accordingly, we generated a model with mixed FAP+ and FAP− tumor cells." (PMID 38975278, 2024). "This hypothesis is also consistent with previous observations that ablation of FAP+/F4/80high TAMs using a diphtheria toxin receptor (DTR) model results in the suppression of tumor growth." (PMID 38275890, 2024). "FAP-targeted NIR-PIT significantly suppressed tumor growth compared with the other groups." (PMID 38555315, 2024). "Our analysis discerned variations in FAP expression between these tumor stages." (PMID 38558814, 2024). "In addition, transferring CAR-T cells that target FAP can substantially diminish FAP-expressing stromal cells, leading to inhibition of tumor growth." (PMID 38693104, 2024). "CAFs overexpressing FAP are frequently found within the tumor stroma across various cancer types." (PMID 39770505, 2024). "One explanation is that the FAP-CAR T cells may extract surface FAP from the conjugated tumor cells through immunological synapse." (PMID 39086477, 2024). "In our study, considering the restrictive expression of FAP, HT1080 cells overexpressing FAP (hFAP-HT1080) was applied to verify that the hFAP-CAR T cells could lyse hFAP-positive tumor cells specifically in vitro and in vivo." (PMID 39086477, 2024).
tumor (continued). "Recently, FAP-targeted positron emission tomography (PET) imaging using a FAP inhibitor (FAPI) has been described as a non-invasive sensitive tool for advanced tumor staging and monitoring and has a promising potential owing to its ability to accurately depict most malignant tumors." (PMID 39188902, 2024). "Both the alpha isoform of FAP and the FR are established tumour markers." (PMID 39048805, 2024). "Also, BALB/c-nu/nu mice were used to examine the affection of host tumor immunity by FAP-targeted NIR-PIT because of familiarity and versatility." (PMID 38555315, 2024). "However, the excised tumor tissues in the JQ1 group exhibited reduced protein levels of FAP‐α, α‐SMA, and IL6, as well as markedly decreased collagen deposition, as revealed by IHC, Masson's trichrome staining, Sirius Red staining, and IF assays." (PMID 38417121, 2024). "Notably, CAF phenotypes positive for FAP (CAFS1 and CAFS4) were associated with processes related to tumor invasion and metastasis." (PMID 38606999, 2024). "In addition to typical HE staining, spheroids were also immunohistological stained with PAX8 as a tumour marker and FAP as a fibroblast marker." (PMID 39384844, 2024). "However, in our study using MDA-MB-231 xenografts, FAP expression was observed in both the tumor cells and the stroma." (PMID 39519118, 2024). "Notably, CAF surface markers ACTA2 and FAP are expressed by other cells within the tumor microenvironment, undermining the precision of CAF-based therapeutic strategies." (PMID 38818409, 2024). "Among these markers, α-SMA and FAP are among the most important markers of fibroblast cells, which are involved in a wide range of CAFs activities, including tumor growth and proliferation, inhibition of the immune system, prevention of drug delivery, metastasis, and angiogenesis." (PMID 39030445, 2024). "However, noticeably, FAP expression was clearly reduced when comparing metastatic tissues with stage IV primary tumour sites." (PMID 39022761, 2024). "To further validate the stable increase of FAP+ CAFs in the tumor microenvironment, we integrated a single-cell validation cohort comprising 79 samples 19, 50, and which demonstrated a gradual increase in the proportion of FAP+ CAFs from AL, HCC, to ICC." (PMID 39239526, 2024). "In keeping with our hypothesis, significant killing of FAP− tumor cells in the upper chamber (SJH‐1 or RKI‐1) was observed when FAP‐CAR‐T cells were present in the lower chamber together with FAP+ tumor cells." (PMID 38975278, 2024). "The fibroblast activation protein (FAP), a type II transmembrane glycoprotein on CAFs, is overexpressed in various malignancies, characterised by a strong desmoplastic reaction that can contribute up to 90% of the tumour mass." (PMID 39598380, 2024). "Therefore, the objective of this study is to create a dual-receptor-targeted peptide heterodimer probe that simultaneously targets SSTR2 and FAP, with the expectation of improving tumor detection sensitivity and extending tracer uptake and retention time." (PMID 39770488, 2024). "When stratifying EC patients based on tumor size, five proteins were significantly increased in patients with tumors larger than 2 cm: endoglin (p = 0.03), FAP (p = 0.001), HB-EGF (p = 0.04), MIA (p = 0.01), and VEGF-A (p = 0.02), when compared to patients with smaller tumors (≤ 2 cm)." (PMID 39511039, 2024). "In the Hu-SCID tumor models, the expression of FBiTE in OVs was found to augment the intratumoral retention and accumulation of T cells while concurrently reducing the level of FAP expression in the treated tumors." (PMID 38464532, 2024). "Notably, there was remarkable heterogeneity of CAF states across the tumor subtypes, with hybrid-NE subtype specifically enriched for FAP+ CAFs." (PMID 38897168, 2024). "In MDA-MB-231 xenografts, FAP expression was noted in both the tumor cells and the stroma." (PMID 39519118, 2024).
tumor (continued). "In this tumor, FAP overexpression was typically observed in the connective tissue, the main location of CAF cells, which led to the conclusion that FAP could be considered a major marker for CAFs." (PMID 39030445, 2024). "Interestingly, our data showed that MpEV-EPC showed the upregulation of vWF, SNAIL, VE-Cadherin, FAP, and ALDH, which are tumor endothelial markers associated with breast TEC." (PMID 38515582, 2024). "Before tumor cells are located in the lymph nodes, they secrete some factors to promote premetastatic lymph nodes by activating fibroblast reticular cells, which differentiate into CAFs and express high levels of FAP." (PMID 38173034, 2024). "Current FAP-targeting small molecules have shown to be successful for imaging with promising tumor-to-background ratios on PET/CT scans in various solid tumors; however, their limited tumor retention time makes these molecules suboptimal for radionuclide therapy." (PMID 39073475, 2024). "The expression of ANO1 in cancer cells, the expression of fibroblast activation protein (FAP) and alpha smooth muscle actin in cancer-associated fibroblasts (CAFs), and the numbers of CD8- and FOXP3-positive tumor-infiltrating lymphocytes (TILs) were evaluated using immunohistochemistry." (PMID 38352864, 2024). "Hence, the tumor retention times of radiotracers, such as FAP-2286, must be improved for use in radionuclide therapy to improve therapeutic outcomes in tumor-bearing mice." (PMID 39660049, 2024). "FAP staining was notably more intense at the tumor margins, aligning with the PET imaging results." (PMID 39519118, 2024). "In fact, the expression of CD31 and FAP in human cancer tissues showed a fairly even distribution across the different tumour stages, suggesting that their expression is important for tumour development, but does not necessarily need to increase at later stages of tumour progression." (PMID 39022761, 2024). "Consecutively, a significant drop of tumor markers could be observed, and the most recent restaging [68Ga]Ga-FAP-2286-PET/CT scan showed a partial remission." (PMID 39338305, 2024). "Additionally, FAP’s role in matrix remodeling and its overexpression in the tumor microenvironment highlight its potential as a therapeutic target in cancer treatment." (PMID 39056788, 2024). "Additionally, CXCL12, secreted by FAP+ CAFs, further inhibits the accumulation of cytotoxic T cells near the tumor, contributing to immune evasion in PDAC." (PMID 38540204, 2024). "In the tumor stroma, FAP is expressed by mesenchymal stem cells." (PMID 39403603, 2024). "FAP-targeted NIR-PIT has great potential to overcome tumor immunosuppression and could be a novel therapeutic adjunct to cancer therapy in CAF+ tumors." (PMID 38555315, 2024). "Thus, there is interest in FAP + CAFs as a potential target for anti-tumor treatments, and existing research suggests that FAP-targeted drugs can exert curative effects in models of most solid tumors." (PMID 39030445, 2024). "α-SMA and FAP-positive CAF subpopulations play important roles in tumor development." (PMID 39430235, 2024). "In addition to the effect of FAP on the immune system, this marker plays an essential role in tumor growth and development, angiogenesis, metastasis, extracellular matrix regeneration, and immune system suppression." (PMID 39030445, 2024). "Moreover, angiopoietin-2, FAP and VEGF-A significantly (p < 0.05–0.001) associated with tumor grade, size, myometrial invasion, and mismatch repair status." (PMID 39511039, 2024). "FAP involves alteration of ECM to promote tumor invasion by the integrin-FAK mediation." (PMID 39579201, 2024). "Notably, COL1A1, COL1A2, and FAP were closely associated with CAF-mediated functions related to carcinogenesis and tumor metastasis." (PMID 39034310, 2024). "In addition, the researchers have developed FAP genetically engineered tumor cell‐derived exosome‐like nanovesicles (eNVs‐FAP)." (PMID 39015555, 2024).